USP15 (ubiquitin specific peptidase 15)
Diseases named in the same sentence as USP15 in open-access papers (continued):
Sharing a sentence is not in itself a finding about the gene and the disease.
bladder cancer (continued). "Consequently, our findings strongly indicate that USP15 is considerably upregulated in bladder cancer tissues and exhibits a significant correlation with various clinical features of bladder cancer." (PMID 38656882, 2024). "Remarkably, our results revealed a significant expression of USP15 in bladder cancer tissues." (PMID 38656882, 2024). "Thus, our results compellingly suggest that by modulating the ubiquitination of BRCC3, USP15 contributes to enhancing the stability of BRCC3 in bladder cancer cells." (PMID 38656882, 2024). "To validate our hypothesis, we performed Western blotting to measure the amount of BRCC3 protein in bladder cancer cells with low USP15 expression." (PMID 38656882, 2024). "Furthermore, we have delved into the potential mechanisms through which USP15 operates in bladder cancer." (PMID 38656882, 2024). "Furthermore, to investigate the impact of USP15 expression on the growth of bladder cancer cells, we individually transfected two types of shRNA into J82 cells." (PMID 38656882, 2024). "Moreover, our study aimed to elucidate the regulatory role of USP15 in the activation of the NF-κB pathway in bladder cancer." (PMID 38656882, 2024). "Our research shows that USP15 plays an important role in bladder cancer, which may be a treated target for the disease." (PMID 38656882, 2024). "Additionally, our findings demonstrated that inhibition of the NF-κB pathway could partially counteract the heightened proliferation, metastasis, and invasive abilities of bladder cancer cells induced by USP15 overexpression." (PMID 38656882, 2024). "To investigate whether USP15 can affect the growth, migration, and invasiveness of bladder cancer by regulating BRCC3, we generated bladder cancer cell models with different expression levels of USP15 and BRCC3 and evaluated their proliferative, migratory, and invasive capabilities." (PMID 38656882, 2024). "However, scarce reports exist pertaining to the potential mechanism by which USP15 may exert its effect in bladder cancer." (PMID 38656882, 2024). "These groundbreaking findings suggest that USP15 holds immense promise as a potential biomarker for bladder cancer patients, while its regulation mechanism may emerge as a prospective therapeutic target for bladder cancer treatment in the future." (PMID 38656882, 2024). "The results revealed a positive correlation between USP15 expression and TNM stage, which encompasses tumor size, lymph node involvement, and metastasis, in bladder cancer patients." (PMID 38656882, 2024). "In conclusion, our study found a new significant mechanism that USP15 regulates the expression of NF-κB through BRCC3, resulting in increased proliferation of bladder cancer cells." (PMID 38656882, 2024). "To further validate the regulatory role of USP15 in NF-κB pathway activity, we introduced the NF-κB signaling pathway inhibitor BAY11-7082 to the bladder cancer cell group with heightened USP15 expression." (PMID 38656882, 2024). "In summary, our study demonstrates that USP15 can activate the NF-κB signaling pathway through BRCC3, thus enhancing the proliferation, migration, and invasiveness of bladder cancer cells." (PMID 38656882, 2024). "BRCA1 is a crucial component of the BRCC3 complex, leading to our conjecture that USP15 may activate the NF-κB pathway by deubiquitinating BRCC3, thereby augmenting its expression and ultimately influencing bladder cancer progression." (PMID 38656882, 2024). "Encouragingly, the results demonstrated an upregulation of USP15 protein expression in bladder cancer tissues compared to normal tissues." (PMID 38656882, 2024).
cardiac hypertrophy (2 papers, 2012 to 2024). "A study on USP15 transgenic mice showed that the upregulation of USP15 exacerbated myocardial hypertrophy by interacting with the SLIM1 protein, cutting the SLIM1 ubiquitin chains and stabilizing the SLIM1 protein." (PMID 38525836, 2024).
gastritis (2 papers, 2024 to 2025). Inflammation of the stomach. "Our current study identified upregulated expression of key TGF-β pathway components (TGF-β1 and USP15) in the gastric mucosa of patients with H. pylori-infected gastritis." (PMID 41035878, 2025). "Furthermore, in the gastric mucosa of the patients with H. pylori-infected gastritis, USP15, ZNF451, TGFB1, and CCNT were identified as participants in the TGF-β signaling pathway, while FYB, HLA-DRB1, ANKRD24, and TMEM35 were implicated in T lymphocyte differentiation and immune response processes." (PMID 41035878, 2025). "In this study, the expression of ANKRD22 and USP15 were downregulated in viral meningitis groups, and ANKRD22 expression is similar to the one found in gastritis." (PMID 38347610, 2024).
Hepatic steatosis (2 papers, 2022 to 2025). Steatosis is a term used to denote lipid accumulation within hepatocytes. "CSN-associated DUBs USP15 and USP48 contribute to NF-κB regulation and cylindromatosis (CYLD) is involved in hepatic steatosis." (PMID 35066747, 2022).
leiomyosarcoma (2 papers, 2023 to 2025). An uncommon, aggressive malignant smooth muscle neoplasm, usually occurring in post-menopausal women. "Additionally, KIF15 recruits and promoted the binding between USP15 and DEK, facilitating the proliferation of leiomyosarcoma cells by preventing DEK degradation." (PMID 40087774, 2025).
liver disease (2 papers, 2022 to 2024). "In light of the essential role of USP15 on p66Shc expression in the liver, specific inhibition of USP15, such as USP15 inhibitor, may represent a powerful and specific therapeutic approach for liver diseases." (PMID 36163170, 2022).
myelodysplastic syndrome (2 papers, 2023 to 2024). A clonal hematopoietic disorder characterized by dysplasia and ineffective hematopoiesis in one or more of the hematopoietic cell lines. "In physiological aging as in Myelodysplastic Syndrome (MDS) and Acute Myeloid Leukaemia (AML), DUBs, including USP7, USP15, and A20, exhibit either increased or decreased expression." (PMID 39108012, 2024). "In summary, we demonstrated for the first time that the USP7, USP15, and UBE2T genes might be related to MDS pathogenesis and prognosis, supporting the importance of these genes in understanding the etiology and prognostic stratification of Myelodysplastic Syndrome." (PMID 37373211, 2023).
papillary thyroid cancer (2 papers, 2024 to 2025). "Moreover, the modulation of CCL2 by factors such as Canagliflozin, PFHxA, USP15, and Vitamin D further connects its involvement in TC development, particularly in association with papillary thyroid carcinoma and Hashimoto’s thyroiditis." (PMID 39928612, 2025).
adenovirus infection (1 paper, 2023). "To further explore whether USP15 mediated hPASMC proliferation and migration in a YAP1/TAZ-dependent manner, we achieved the depletion of YAP1 or TAZ in USP15-overexpressing hPASMCs by corresponding adenovirus infection." (PMID 36635430, 2023).
AIDS (1 paper, 2022). A syndrome resulting from the acquired deficiency of cellular immunity caused by the human immunodeficiency virus (HIV). "Conversely, the interaction between USP15 and the HIV-1 Gag and Nef (necessary for AIDS pathogenicity) inhibits HIV-1 replication." (PMID 35632621, 2022).
autism (1 paper, 2014). Persistent deficits in social interaction and communication and interaction as well as a markedly restricted repertoire of activity and interest as well as repetitive patterns of behavior. "Defects in other ubiquitin specific peptidases, for example USP15, have been associated with autism." (PMID 25411581, 2014).
autoimmune disease (1 paper, 2022). A disorder resulting from loss of function or tissue destruction of an organ or multiple organs, arising from humoral or cellular immune responses of the individual to their own tissue constituents. "Further, USP15 is a host factor for hepatitis C virus (HCV) propagation and participates in the differentiation of Th17 cells, which are involved in immunity against pathogens and autoimmune diseases, including MS and psoriasis." (PMID 35632621, 2022).
bladder tumors (1 paper, 2024). "In our research, we identified that USP15 was aberrantly elevated in bladder tumor tissues and associated with poorer prognosis." (PMID 38656882, 2024). "To delve deeper into the correlation between USP15 expression and clinicopathological features in bladder tumors, we conducted an investigation to examine the association between USP15 expression and the progression of clinicopathological features." (PMID 38656882, 2024). "To comprehensively study the impact of USP15 on bladder tumors in vivo, we established nude mouse models for conducting tumor experiments." (PMID 38656882, 2024). "In summary, our findings provide compelling evidence demonstrating the critical role of USP15 in promoting the growth, migration, and invasion of bladder tumor cells in vitro." (PMID 38656882, 2024). "To validate these findings, we performed Western blotting to assess the protein levels of USP15 in both bladder tumor tissue and adjacent normal tissue." (PMID 38656882, 2024). "To comprehensively investigate the role of USP15 in bladder tumors, we conducted an analysis of USP15 expression in pan-cancer tissues utilizing the TIMER database." (PMID 38656882, 2024). "Subsequent colony formation assays revealed a substantial decrease in the growth ability of bladder tumor cells upon downregulation of USP15 expression, as compared to the control group." (PMID 38656882, 2024). "The results demonstrated a significant inhibition of both migration and invasiveness in bladder tumor cells following USP15 inhibition." (PMID 38656882, 2024). "Significantly, our investigations provide unprecedented evidence of USP15’s abundant presence in both in vivo and in vitro bladder tumor tissues." (PMID 38656882, 2024). "Moreover, this heightened USP15 expression correlates with enhanced growth, migration, and invasion capacity of bladder tumor cells." (PMID 38656882, 2024). "This led us to hypothesize that USP15 might impact bladder tumor progression by influencing the NF-κB pathway." (PMID 38656882, 2024). "Moreover, we employed Transwell migration and invasion assays to ascertain the effect of USP15 inhibition on the migratory and invasive properties of bladder tumor cells." (PMID 38656882, 2024). "Notably, pharmacological inhibition of the NF-κB pathway attenuates the overexpression of p-P65 in USP15-overexpressing bladder tumor cells." (PMID 38656882, 2024). "Further exploration involved quantifying USP15 mRNA levels in non-tumor bladder tissues, which unveiled a comparatively higher expression of USP15 in bladder tumors." (PMID 38656882, 2024). "For the first time, our study unveils the remarkable disparity in USP15 expression between bladder tumor tissues and adjacent noncancerous tissues, with higher levels detected in the former." (PMID 38656882, 2024).
breast tumor (1 paper, 2021). "The results of immunohistochemistry assay showed that USP15 expression was higher in human breast tumor tissues than in adjacent tissues." (PMID 33771975, 2021).
cerebral malaria (1 paper, 2024). A sequestration of Plasmodium falciparum in the brain, which can cause coma and/or seizures. "Previous studies in experimental cerebral malaria and autoimmune encephalomyelitis models have implicated USP15 as a regulator of type 1 IFN responses in innate immune and T cells." (PMID 37874479, 2024). "Mice with experimental cerebral malaria which carried a point mutation in the Usp15 gene in a heterozygous fashion had lower survival rates than homozygous littermates, but still performed significantly better than WT." (PMID 37874479, 2024). "A recent study identified the DUB USP15 as a key regulator in the pathogenesis of neuroinflammation in experimental cerebral malaria and experimental autoimmune encephalomyelitis." (PMID 37874479, 2024). "The rationale of our study was based on the impact seen after reduction of USP15 in the experimental cerebral malaria and autoimmune encephalomyelitis models." (PMID 37874479, 2024). "This shows that already a ~ 50% reduction of USP15 protein expression had anti-inflammatory effects in experimental cerebral malaria, indicating that a reduction to ~ 10% of the baseline level as observed in our study, should at least in theory be enough to induce clear effects." (PMID 37874479, 2024). "In summary, our data indicate that the lack of USP15, despite its positive effect on other inflammatory diseases of the CNS (experimental cerebral malaria and experimental autoimmune encephalomyelitis), does not have a positive effect in mTLE." (PMID 37874479, 2024).
Cirrhosis (1 paper, 2025). A chronic disorder of the liver in which liver tissue becomes scarred and is partially replaced by regenerative nodules and fibrotic tissue resulting in loss of liver function. "In summary, our findings demonstrate that USP15 is highly expressed in HCC, with levels positively correlated with serum AFP levels, tumor TNM stage, tumor size, cirrhosis, and microvascular invasion, and negatively correlated with patient overall survival." (PMID 39794359, 2025). "In addition, analysis of patient data indicated that USP15 expression level was positively correlated with tumor TNM stage, tumor size, cirrhosis, and microvascular invasion, while negatively correlated with patient overall survival." (PMID 39794359, 2025).
Listeria infection (1 paper, 2017). "In response to Listeria infection, the Usp15−/− T‐cell reconstituted hosts had reduced bacterial load in the liver and increased survival rate, implying that USP15 is dispensable for T‐cell function under infectious challenges." (PMID 28544818, 2017).
macrodactyly (1 paper, 2025). "Targeted inhibition of USP15 may serve as a promising therapeutic approach for treating macrodactyly." (PMID 41052995, 2025).
Marfan syndrome (1 paper, 2021). A disorder of the connective tissue. "Although some diseases such as Marfan syndrome have reported the effect of ERK on the TGF-β signaling pathway, we deeply found that ERK2 can affect this pathway through USP15, which is of great significance for supplementing the classical TGF-β signaling pathway." (PMID 33726807, 2021).
Moyamoya disease (1 paper, 2017). Moyamoya disease (MMD) is a rare intracranial arteriopathy involving progressive stenosis of the cerebral vasculature located at the base of the brain causing transient ischemic attacks or strokes. "We found that the long isoform of USP15 predominantly recognizes and deubiquitylates mysterin, a large ubiquitin ligase associated with the onset of moyamoya disease." (PMID 28276505, 2017). "Further investigation of these issues, as well as the potential involvement of USP15 in moyamoya disease, is warranted." (PMID 28276505, 2017).
myeloid malignancies (1 paper, 2023). "Furthermore, Niederkorn and collaborators found that TIFAB (fork-associated B domain), a protein commonly involved in myeloid malignancies, regulates USP15 signaling to substrates in hematopoietic cells." (PMID 37373211, 2023).
myocardial infarction (1 paper, 2020). Gross necrosis of the myocardium, as a result of interruption of the blood supply to the area, as in coronary thrombosis. "In another study, the downregulation of lncRNA 2810403D21Rik/Mirf (myocardial infarction-regulatory factor) was found to alleviate cardiac injury via up-regulating miR-26a, which targeted the Usp15 (ubiquitin specific peptidase 15)." (PMID 32315985, 2020).
Right ventricular hypertrophy (1 paper, 2023). In this case the right ventricle is more muscular than normal, causing a characteristic boot-shaped (coeur-en-sabot) appearance as seen on anterior- posterior chest x-rays. "The preventative/reversal knockdown of USP15 in vivo evidently inhibited pulmonary vascular wall thickening, right ventricular hypertrophy, and YAP1/TAZ signaling in animals with experimental PH." (PMID 36635430, 2023). "Accordingly, in this study, obvious right ventricular hypertrophy manifested as a vastly elevated RV/LV + S ratio was validated after SuHx and MCT induction, and it was significantly alleviated after USP15 knockdown." (PMID 36635430, 2023).
skin cancer (1 paper, 2022). "These include ubiquitin-specific protease 15(USP15), a key carcinogen protein highly expressed in skin cancer and blood-associated tumors." (PMID 36213818, 2022).
status epilepticus (1 paper, 2024). Status epilepticus is defined as a continuous seizure lasting more than 30 min, or two or more seizures without full recovery of consciousness between any of them. "In conclusion, the effect of ihKA on the transcriptome was very similar in Usp15−/− and in WT mice, thus ruling out the hypothesis that a constitutive deletion of Usp15 could rescue transcriptomic changes caused by ihKA-induced status epilepticus." (PMID 37874479, 2024). "To analyze acute effects of Usp15 knockout after status epilepticus, we used a constitutive Usp15 KO mouse line (Usp15−/−) and respective WT littermates (Usp15+/+, referred to as WT in the following)." (PMID 37874479, 2024). "In contrast, in our study on Usp15−/− mice investigating the acute effects of status epilepticus, the cell death and inflammatory response might have been too extensive to be impacted by USP15." (PMID 37874479, 2024). "First, we tested the hypothesis whether constitutive deletion of Usp15 affects hippocampal damage and/or the inflammatory reaction early (4 days) after status epilepticus." (PMID 37874479, 2024). "Together, these results indicate that despite strong alterations between the contralateral and the KA-injected side in both genotypes, USP15 deficiency does not affect the pattern of granule cell dispersion, cell loss, or glia activation shortly after status epilepticus." (PMID 37874479, 2024). "We show that the severity of status epilepticus is unaltered in mice constitutively lacking Usp15 compared to wild types." (PMID 37874479, 2024). "While we were not expecting to reduce severity of status epilepticus itself, we followed the hypothesis that consequential neuroinflammatory pathways could be dampened by downregulation of Usp15." (PMID 37874479, 2024).
thyroid cancer (1 paper, 2024). "Comparably, pharmacological inhibition of BRAF or ERK1/2 also significantly down-regulated USP15 expressions in BRAFV600E-mutated human thyroid cancer cells." (PMID 38750011, 2024).
thyroid tumor (1 paper, 2024). A benign or malignant neoplasm affecting the thyroid gland. "Here, the authors show that MAPK activation upregulates USP15 to promote deubiquitylation and stability of TBX3, a transcription factor implicated in thyroid development and differentiation, driving tumorigenesis in a BRAFV600E thyroid tumor model." (PMID 38750011, 2024). "Tbx3 and Usp15 deficiency both lead to differentiation augmentation, exemplified with excessive Tpo, Nis, and Tg in thyroid folliculogenesis and regain the same factors in BRAFV600E-driven thyroid tumor development." (PMID 38750011, 2024).
triple-negative breast carcinoma (1 paper, 2022). An invasive breast carcinoma which is negative for expression of estrogen receptor (ER), progesterone receptor (PR), and human epidermal growth factor receptor 2 (HER2). "Therefore, we speculate that USP15 may be a key protein in the prediction of triple-negative breast cancer." (PMID 36213818, 2022).